FBXO22 (F-box protein 22)
Diseases named in the same sentence as FBXO22 in open-access papers (continued):
Sharing a sentence is not in itself a finding about the gene and the disease.
cancer (25 papers, 2015 to 2026). A tumor composed of atypical neoplastic, often pleomorphic cells that invade other tissues. "FBXO22 has been reported to be highly expressed and linked to poor prognosis in several human cancers." (PMID 36127346, 2022). "Taken together, our pan-cancer analyses revealed correlations between FBXO22 expression, methylation, mutation and clinical prognosis, and immune cell infiltration, which contribute to a better understanding of the role of FBXO22 in tumorigenesis." (PMID 35141150, 2021). "In this study, we explored the correlations between clinical prognosis and FBXO22 expression, methylation, and mutation in 33 cancer types from the TCGA database using bioinformatic analysis." (PMID 35141150, 2021). "We also confirmed that high expression of FBXO22 was associated with lower TIL levels in some cancer types, including LUAD, LUSC, and SARC, as established using different evaluation algorithms." (PMID 35141150, 2021). "Taken together, these data indicate that FBXO22 expression is associated with poor prognosis in cancer." (PMID 35141150, 2021). "We subsequently explored whether FBXO22 methylation was associated with prognosis among people with cancer using the DNMIVD tool." (PMID 35141150, 2021). "However, in a pan-cancer context, we found that high FBXO22 expression was associated with poor OS and RFS, as determined using Kaplan-Meier analysis." (PMID 35141150, 2021). "Accumulating evidence indicates that FBXO22 plays an essential role in the progression of human cancer." (PMID 38519492, 2024). "Accumulating evidence indicates that FBXO22 plays an essential role in a broad range of human cancers." (PMID 36127346, 2022). "Using the UALCAN tool, we observed that the FBXO22 promoter methylation level was significantly decreased in multiple cancer tissues compared with healthy tissues." (PMID 35141150, 2021). "In the future, it will be important to investigate the specific role of FBXO22 in cancer immune regulation, especially in LUAD, LUSC, and SARC." (PMID 35141150, 2021). "To explore the role of FBXO22 expression in human cancer, we performed a pan-cancer analysis of FBXO22 using Gene Expression Quantification data of 33 cancers from TCGA database." (PMID 35141150, 2021). "Here, we performed a pan-cancer analysis of FBXO22 using TCGA database to explore the role of FBXO22-mediated ubiquitination in cancer." (PMID 35141150, 2021). "We also used the cBioPortal tool to analyze the genetic alteration status of FBXO22 in different cancer types from the TCGA cohorts." (PMID 35141150, 2021). "Here, we performed a pan-cancer analysis to explore the role of FBXO22 in 33 cancer types using multiomic data from The Cancer Genome Atlas (TCGA)." (PMID 35141150, 2021). "In this review, we summarize the regulatory factors and downstream targets of FBXO22 in cancers, discuss its functions in tumorigenesis, and further highlight the alteration of FBXO22 expression in a variety of human malignancies." (PMID 32793396, 2020).
cancer (continued). "Thus, we asked whether FBXO22 was one of the reasons that caused nuclear PTEN loss in cancers." (PMID 32249768, 2020). "In the following sections, we will describe the regulatory factors and downstream targets of FBXO22 in a variety of human cancers, and the alteration of its expression levels in human cancer tissues." (PMID 32793396, 2020). "To better clarify the expression pattern and the correlation with patient survival of FBXO22 in human cancers, we examined FBXO22 mRNA expression using the data obtained from the TCGA database." (PMID 32793396, 2020). "By comparing samples with 35% highest and lowest FBXO22 expression, we also observed significant inverse correlations between FBXO22 expression and overall patient survival in TCGA datasets of several cancer types." (PMID 32249768, 2020). "For this purpose, we firstly examined the expressional pattern of FBXO22 in all cancer types of The Cancer Genome Atlas (TCGA) database." (PMID 32249768, 2020). "Further exploring the role of FBXO22 in the initiation and progression of other types of cancer will shed light on the role of FBXO22 in tumorigenesis." (PMID 31217475, 2019). "FBXO22 is an E3 ligase that ubiquitinates the PD-L1 protein in cancer cells." (PMID 41356798, 2026). "FBXO22 plays a critical role in cancer progression by regulating the degradation of key proteins." (PMID 40534867, 2025). "High FBXO22 expression is correlated with poor overall survival in numerous cancers." (PMID 39153212, 2024). "We speculate that the different functions of FBXO22 might depend on the changes in microenvironments in different cancers." (PMID 38519492, 2024). "Some key substrates of FBXO22 have been found in a variety of cancers." (PMID 38519492, 2024). "Interestingly, several studies have reported that FBXO22 plays an antitumor role in multiple cancer types." (PMID 39153212, 2024). "However, other studies have also demonstrated that FBXO22 can inhibit the progression of many cancers by catalyzing its substrate degradation." (PMID 38519492, 2024). "F-box-only protein 22 (FBXO22) is a ubiquitin ligase that is responsible for recruiting and binding members of the F-box protein family of substrates, participating in the initiation, progression, recurrence, and metastasis of various human malignant tumors." (PMID 38519492, 2024). "Furthermore, Fbxo22 is an epigenetic multiplayer with its strikingly crucial role unveiled in cancer development and therapeutics." (PMID 36112263, 2023). "We used the UALCAN tool to analyze FBXO22 methylation in various cancers from TCGA database." (PMID 35141150, 2021). "We also analyzed a group of factors, such as gene expression, survival status, DNA methylation, genetic alteration, immune infiltration, and relevant cellular pathway, to investigate the potential molecular mechanism of FBXO22 in the pathogenesis or clinical prognosis of different cancers." (PMID 35141150, 2021). "This may be an important explanation for the high level of FBXO22 expression in a variety of cancer types." (PMID 35141150, 2021). "However, the role of FBXO22-mediated ubiquitination of substrates in human cancer is poorly understood." (PMID 35141150, 2021). "Nevertheless, the impact of FBXO22 expression on survival outcomes varied depending on the cancer type, and variation in data sources may also lead to variable results for the same cancer type." (PMID 35141150, 2021). "Therefore, overall, we can conclude that high FBXO22 expression resulted in worse survival outcomes in most cancer types." (PMID 35141150, 2021). "The results of our analysis showed that FBXO22 was highly expressed in multiple cancer types." (PMID 35141150, 2021). "Finally, we provide novel insights for future perspectives on targeting FBXO22 as a promising strategy for cancer therapy." (PMID 32793396, 2020). "The expression level of FBXO22 in various types of cancers has also been determined." (PMID 32793396, 2020).
cancer (continued). "Which targets of FBXO22 are pivotal for cancer development and malignant progression?" (PMID 32793396, 2020). "As expected, FBXO22 showed predominant nuclear localization in both cancer and normal tissues." (PMID 32249768, 2020). "Therefore, FBXO22 is potentially involved in development, differentiation and cancer via controlling KDM4A stability, leading to regulation of H3K9 and H3K36 methylation, which are important factors to maintain normal cellular function." (PMID 32793396, 2020). "To ask whether FBXO22 promotes cancer cell growth through LKB1/AMPK/mTOR pathway, we performed further analysis of downstream signaling pathways using p-AMPK(Thr172), p-Raptor(Ser792) and p-P70S6K(Thr389), as indicators of mTOR activation." (PMID 31217475, 2019). "Inhibition or down-regulation of FBXO22 by gene therapy might be beneficial in patients with malignant tumors." (PMID 26087183, 2015). "However, the expression and roles of FBXO22 in other types of human cancers remain to be determined." (PMID 26087183, 2015). "Hence, we explored the genetic alteration status of FBXO22 in human cancers." (PMID 35141150, 2021). "This may be related to the high FBXO22 expression in multiple cancer types." (PMID 35141150, 2021). "However, until now, it has been unclear whether FBXO22 plays a critical role in the pathogenesis of different cancers via a common molecular mechanism." (PMID 35141150, 2021). "How the inhibitors of FBXO22 could be developed and discovered for cancer therapy?" (PMID 32793396, 2020). "However, it is unclear whether miR-155 targets FBXO22 in human cancer cells, which is required to further determine." (PMID 32793396, 2020). "FBXO22 also regulates the expression of several tumorigenic proteins including PD-L1, via SCFFBXO22-targeted substrate for proteasomal degradation in cancer cells." (PMID 40263598, 2025). "FBXO22 targets several substrates, including PD-L1 and PTEN, for degradative ubiquitination in cancer cells." (PMID 40263598, 2025). "A study revealed that FBXO22 triggers the ubiquitination and degradation of CD147, thereby reversing cancer cells’ resistance to cisplatin." (PMID 40534867, 2025). "FBXO22, an F-box receptor subunit of the SCF E3 ligase, has recently been considered to play a key role in many aspects related to cancer development and therapeutic response." (PMID 38519492, 2024). "The abundance of most TIL types was positively correlated with FBXO22 expression in both GBM and UVM cancers; however, the abundance of almost all TIL types in other cancers was negatively correlated with expression of FBXO22." (PMID 35141150, 2021). "Our studies suggest that compounds that could modify the BTB or DNA-binding domains of BACH1 have the potential to promote the ubiquitination and degradation of BACH1 by FBXL17 or FBXO22, thereby, ameliorating BACH1-mediated cancer metastasis." (PMID 38895309, 2024). "We found a significant negative correlation between FBXO22 expression and chemokines or receptors in almost all cancers." (PMID 35141150, 2021). "We found that FBXO22 expression was negatively correlated with the abundance of multiple TIL types, including NK T cells, in most cancer types, whereas FBXO22 methylation was positively correlated with the abundance of TILs, as established using TISIDB database analysis tools." (PMID 35141150, 2021). "Intriguingly, in most cancer types, FBXO22 expression was upregulated in cancer tissues compared to normal tissues." (PMID 32249768, 2020). "First, LKB1 protein level do not change in the condition of FBXO22 knockdown or over-expression in cancer cell lines." (PMID 31217475, 2019). "Inhibition of CDK5 elevated the expression of FBXO22 and subsequently inhibited PD-L1 protein levels, indicating that CDK5 was an upstream regulator of FBXO22 and that CDK5 inhibitors could increase the efficacy of immunotherapy in cancer cells." (PMID 36733484, 2023).
cancer (continued). "It has been reported that ubiquitin ligase FBXO22 mediates the multiubiquitination and degradation of CD147 by interacting with the intracellular domain CD147-ICD of transmembrane glycoprotein CD147, thus reversing the cisplatin resistance of SMMC-7721, Huh-7 and A549 cancer cells." (PMID 32508530, 2020). "However, a systematic assessment of the role of FBXO22 across human cancers is lacking." (PMID 35141150, 2021). "In circumstances with low E1 and E2 levels, Fbxo22, as a negative regulator disassembling KDB4B, might not be required to maintain the homeostasis of ER-positive cancer cells, resulting in Fbxo22 being naturally downregulated in ILCs in postmenopausal women." (PMID 38180699, 2024).
infection (1 paper, 2012). The state of being infected such as from the introduction of a foreign agent such as serum, vaccine, antigenic substance or organism. "Infection of these transfected cells with ΔgogB complemented with the full-length GogB-2HA showed that FBXO22 was precipitated by GogB-2HA in the absence or presence of Skp1." (PMID 22761574, 2012).
FBXO22 also shares sentences with these, for which no sentence is quoted: lung squamous cell carcinoma (2 papers); triple-negative breast carcinoma (2); acute myeloid leukemia (1); breast tumor (1); cervical squamous cell carcinoma (1); cervical squamous intraepithelial lesion (1); cervical tumor (1); endometrial carcinoma (1); invasive lobular carcinoma (1); ovarian cancer (1); sarcoma (1); uterine corpus endometrial carcinoma (1).